NECTIN2 (nectin cell adhesion molecule 2)
Diseases named in the same sentence as NECTIN2 in open-access papers (continued):
Sharing a sentence is not in itself a finding about the gene and the disease.
Alzheimer disease (16 papers, 2015 to 2026). A progressive, neurodegenerative disease characterized by loss of function and death of nerve cells in several areas of the brain leading to loss of cognitive function such as memory and language. "In this paper, we performed causal mediation analysis (CMA) to explore potentially causal relationships among the rs6859 polymorphism in the NECTIN2 gene, pTau, and AD using the Alzheimer’s Disease Neuroimaging Initiative (ADNI) data." (PMID 39165837, 2024). "In conclusion, this study revealed a new potential causal relationship between pTau-181 and AD that partly explains the association of the rs6859 polymorphism in the NECTIN2 gene with Alzheimer’s disease." (PMID 39165837, 2024). "Genome-wide association study revealed that the human NECTIN-2 gene is associated with Alzheimer's disease." (PMID 37829206, 2023). "Mendelian randomization analysis implicated higher levels of NECTIN2, a protein mediating viral entry into neuronal cells, with higher Alzheimer’s disease (AD) risk (p = 2.5E-26)." (PMID 37923804, 2023). "Comparison of PV-AEF components between nectin-2-deficient and wild-type mice may provide insight into the mechanisms for the degeneration of PV-AEF and pathological aspect of Alzheimer's disease." (PMID 37829206, 2023). "For Alzheimer’s disease, allelic heterogeneity was observed in the genomic locus containing NECTIN2, TOMM40, APOE and APOC1, which has been reported before and reflects the fact that different APOE haplotypes ε2, ε3 or ε4 can be risk factors or protective factors for Alzheimer’s disease." (PMID 34326310, 2021). "From the literature reviews, we can see that NECTIN2 has inflammatory roles in the brain, TOMM40 causes neuro-inflammation and Alzheimer’s disease and APOC4-APOC2 may affect the TOMM40-APOE-APOC2 axis, related to Alzheimer’s disease." (PMID 38672162, 2024).
hepatocellular carcinoma (11 papers, 2017 to 2024). A malignant tumor that arises from hepatocytes. "Nectin-like-5 and Nectin-2, ligands of DNAM-1, are expressed on most hepatocellular carcinoma (HCC) cell lines." (PMID 28894450, 2017).
viral infections (11 papers, 2012 to 2025). "NECTIN2 is involved in adherens junction, which is important to maintain blood‐brain barrier and to prevent the spread of viral infections." (PMID 32400971, 2020). "Nectin-2 (Nectin cell adhesion molecule 2) is a membrane component of adherens junctions that serves as an entry point for certain herpesviruses and may mediate response to the viral infections." (PMID 39165837, 2024). "Indeed, recombinant nectin-2-Fc was found to be weakly bound to gB-HA in a nectin-2 direct binding assay, and the efficiency of viral infection was low, even in the ex6 C7 cells, in which the mean fluorescence intensity was approximately three times higher than that in the HSB2-cont cells." (PMID 35062364, 2022). "Virus-infected cell recognition by NK cells is not pathogen-specific in the vast majority of cases, but rather depends on recognition of cell ligands to activating receptors that are induced by virus infection (e.g. PVR, Nectin-2, MIC-a, MIC-b, ULBPs, B7-H6 etc)." (PMID 33861802, 2021). "While EGFR and Nectin2 were not enriched, Neo1 was enriched 2.78-fold upon virus infection." (PMID 40623098, 2025). "Although nectin-2 might not be an entry receptor comparable to CD134, induction of virus infection via the overexpression of nectin-2 suggests that nectin-2 is involved in binding as well as the entry process." (PMID 35062364, 2022).
colorectal cancer (9 papers, 2019 to 2025). A primary or metastatic malignant neoplasm that affects the colon or rectum. "Numerous publications indicate overexpression of nectin-2 in epithelial-origin tumors and adenocarcinomas, including colorectal cancer." (PMID 37958883, 2023). "NECTIN2 was important for invasion and metastasis in colorectal carcinoma." (PMID 30970615, 2019).
neuroblastoma (9 papers, 2013 to 2025). Neuroblastoma (NB) is the most common solid, extracranial childhood tumor. "In conclusion, we have constructed a comprehensive atlas of the neuroblastoma immune environment and identified functionally relevant targets, including the NECTIN2-TIGIT axis, for (combination) immunotherapies." (PMID 38181797, 2024). "analyze the immune landscape of neuroblastoma pre- and post-chemotherapy and identify the NECTIN2-TIGIT axis as a crucial immune checkpoint, which correlates with dysfunction of T/NK cells." (PMID 38181797, 2024). "Subsequent functional validation experiments identified the NECTIN2-TIGIT axis as promising target for neuroblastoma immunotherapy." (PMID 38181797, 2024). "In the current study, we demonstrate that serum Nectin2 level is increased in NB patients compared with that in healthy controls and Nectin2 level is correlated with neuroblastoma international neuroblastoma staging system (INSS) classification." (PMID 36916296, 2023). "Taken together, the NECTIN2-TIGIT axis may regulate T cell function in neuroblastoma and represents a promising target for therapeutic intervention." (PMID 38181797, 2024). "In addition, the over-expression of Nectin-2 in cell lines derived from various types of cancers and in neuroblastoma, myeloid and lymphoblastic leukemias, gastric cancer, and colon cancer suggests the possibility for the application of anti-Nectin-2 antibody to treat various cancer types." (PMID 23758976, 2013). "STRING database analysis predicted that ANXA2 binds to STAT3, and thus, we speculate that STAT3 may be involved in the downstream signalling pathway of Nectin2 and ANXA2 during neuroblastoma pathogenesis." (PMID 36916296, 2023). "Although we detected elevated levels of Nectin2 in the serum of NB patients, enhancement of serum Nectin2 levels does not necessarily indicate Nectin2 overexpression in neuroblastoma." (PMID 36916296, 2023).
pancreatic cancer (9 papers, 2015 to 2025). "Our study showed that NECTIN2 is another important ligand of TIGIT in pancreatic cancer." (PMID 40855305, 2025). "Therefore, in addition to TGF-β1, PVR and nectin-2 in pancreatic cancer-derived EVs could also impair NK cell function." (PMID 31234517, 2019). "By Western blotting, we found that pancreatic cancer-derived EVs displayed a variety of immune regulatory molecules, such as TGF-β1, nectin-2, and PVR." (PMID 31234517, 2019). "Apart from TGF-β1, pancreatic cancer-derived EVs also contained multiple other immune regulatory factors, such as PVR and nectin-2, which could be delivered as inhibitory signals to NK cells." (PMID 31234517, 2019). "Interestingly, enrichment of some molecules, including TGF-β1, nectin-2, and PVR, was identified in pancreatic cancer-derived EVs by Western blotting." (PMID 31234517, 2019).
atherosclerosis (8 papers, 2015 to 2025). A disease characterized by the build-up of fatty material and calcium deposition in the arterial wall resulting in partial or complete occlusion of the arterial lumen. "PECAM-1 has been involved in the pathophysiology of inflammation, coagulation, and atherosclerosis, and NECTIN-2 has been associated to atherogenesis." (PMID 38673963, 2024). "Previous studies demonstrated that the downregulation of NECTIN2 by siRNA led to an increase in LDL cholesterol uptake in cells, and NECTIN2 knockout mice showed a reduction in atherosclerosis." (PMID 38895099, 2024).
glioma (8 papers, 2013 to 2024). A benign or malignant brain and spinal cord tumor that arises from glial cells (astrocytes, oligodendrocytes, ependymal cells). "Despite MYXV-mediated down-regulation of Nectin-2 we still saw enhanced NK cell-mediated killing of glioma cells." (PMID 23762498, 2013). "The fact that NK cell-mediated killing of glioma cells was enhanced by MYXV, despite down-regulation of Nectin-2, suggests that MHC I down-regulation may be the mechanism of enhanced NK cell-mediated lysis." (PMID 23762498, 2013).
lung cancer (8 papers, 2021 to 2025). A malignant neoplasm involving the lung. "Remarkably, inhibition of SIRT7 also enhanced the repression of ARF target genes in ARF-positive Calu-3 lung cancer cells further supporting the hypothesis that SIRT7 controls expression of Nectin2, XRCC1, and SUPT5H in an ARF-dependent manner." (PMID 38870055, 2024).
acute myeloid leukemia (7 papers, 2018 to 2025). Acute myeloid leukemia (AML) is a group of neoplasms arising from precursor cells committed to the myeloid cell-line differentiation. "Necl-5 and nectin-2 are being investigated as potential therapeutic targets in acute myeloid leukemia (AML)." (PMID 40244005, 2025). "In contrast, nectin-2 is currently being investigated for its potential use in the treatment of acute myeloid leukemia, and the results appear to be promising." (PMID 40244005, 2025). "The most advanced research on nectin-2 has been conducted in patients with acute myeloid leukemia." (PMID 40244005, 2025).
dementia (6 papers, 2018 to 2026). Loss of intellectual abilities interfering with an individual's social and occupational functions. "Along with TOMM40 and APOE4 on the same chromosome, NECTIN2 has been shown to be involved in longevity and dementia." (PMID 38408961, 2024). "However, a case–control GWAS (with family history of dementia as exclusion criteria in cases) with 9 of 13 significant SNPs in the APOE region implicated APOE, APOC1, TOMM40, and NECTIN2 in the prediction of clinical diagnosis of AD in the Chinese population." (PMID 40352683, 2025). "Furthermore, NECTIN2 gene is located in a major dementia locus along with TOMM40 and APOE genes." (PMID 38408961, 2024). "Significantly associated proteins at a false discovery rate (FDR) < 0.05 in both models 1 and 2 were CGREF1, MET, ALDH2, NECTIN2, APOC1, APOE and FOSB for HFRS, and CDK and POF1B for HFRS without dementia." (PMID 40764432, 2025).
leukemia (6 papers, 2013 to 2025). A malignant (clonal) hematologic disorder, involving hematopoietic stem cells and characterized by the presence of primitive or atypical myeloid or lymphoid cells in the bone marrow and the blood. "In sharp contrast, stem cell gene, Cd34; lineage gene, Gata2; and leukemia stem cell regulator, Ikzf2; as well as Tnfaip3, Pvr (Cd155), and Nectin2 (Cd112), were upregulated in Vav-cre Tet2fl/flTp53fl/fl GMPs." (PMID 40111422, 2025). "Relevant receptors involved in anti-leukemia activity are NKp46, NKp30, and NKp44 (collectively called natural cytotoxicity receptors, NCR), whose surface-bound ligands are still not completely defined, NKG2D interacting with MICA/B and ULBPs, and DNAM-1 recognizing PVR (CD155) and Nectin-2 (CD112)." (PMID 32764469, 2020).
cognitive decline (5 papers, 2023 to 2025). "Despite the strong association between NECTIN2 gene and AD, the exact biological mechanisms behind the association between NECTIN2 gene and cognitive decline remain unknown." (PMID 38408961, 2024). "In this study, we investigated whether the SNP rs6859 in nectin cell adhesion molecule 2 (NECTIN2) gene (a major risk factor for AD) influences trajectories of cognitive decline in older participants from the Alzheimer’s Disease Neuroimaging Initiative (ADNI)." (PMID 38408961, 2024). "For example, a study highlights the involvement of APOE and its neighbouring genes (TOMM40, NECTIN2, BCAM) in AD and cognitive decline, partly reinforcing our findings of shared genetic susceptibility between vascular calcification and AD-related traits." (PMID 40149595, 2025).
COVID-19 (5 papers, 2022 to 2024). A disease caused by infection with severe acute respiratory syndrome coronavirus 2. "In patients with severe COVID-19, infected cells and monocytes upregulate their surface expression of NECTIN2/CD112, leading to NK cell exhaustion and, hence, to SARS-CoV-2 escape." (PMID 38674024, 2024). "NK cells from patients with severe COVID-19 internalize DNAM-1 following binding to NECTIN2/CD112, whereas TIGIT inhibits NK cells following its low-affinity binding." (PMID 38674024, 2024). "In patients with severe COVID-19, infected cells and monocytes upregulate the surface expression of NECTIN2/CD112." (PMID 38674024, 2024).
glioblastoma (5 papers, 2013 to 2025). The most malignant astrocytic tumor (WHO grade IV). "It has been reported previously that NK cells recognize and kill human glioblastoma cells that express high levels of nectin-2." (PMID 30217189, 2018). "Nectin-2, like PVR, binds to DNAM-1, a NK cell co-activating receptor involved in NK lysis of human glioblastoma." (PMID 23762498, 2013). "It has been reported that glioblastoma (GBM) CSCs are vulnerable to IL-2/IL-15-activated NK cells due to their expression of cytotoxicity receptors and ligands (i.e., PVR and Nectin-2) and the reduction of MHC-I molecules on their surface." (PMID 33530455, 2021).
gallbladder cancer (4 papers, 2015 to 2025). "The expression of nectin-2 and nectin-4 has been reported to be associated with a poor prognosis in gallbladder carcinoma and non-small-cell lung carcinoma, respectively." (PMID 25690753, 2015).
myeloid leukemia (4 papers, 2020 to 2024). A clonal proliferation of myeloid cells and their precursors in the bone marrow, peripheral blood, and spleen. "DNAM1 blockade did very little in any of our assays, in opposition to previous reports showing DNAM-1 activation of NK cells via interaction with CD112 (Nectin-2) and CD155 (PVR) on myeloid leukemias." (PMID 35222407, 2022).
colon carcinoma (3 papers, 2013 to 2023). "Based on current knowledge concerning the observed molecular profile differences between right and left colon cancers, it appears interesting that nectin-2 may be associated with tumor sidedness." (PMID 37958883, 2023).
coronary artery disease (3 papers, 2015 to 2025). "There are genetic associations between the human NECTIN2 gene and both Alzheimer's and coronary heart disease." (PMID 39919333, 2025).
Infertility (3 papers, 2019 to 2023). "In mice with nectin-2 deficiency, malformations in spermiogenesis, impaired sperm morphogenesis and male-specific infertility have been observed." (PMID 32580404, 2020). "As a anchor junction protein, Nectin-2 is mainly expressed in Sertoli cells and elongated spermatids, and Nectin-2 knockout mice had normal sperm titers but exhibited infertility phenotype due to serve spermatozoa malformation, suggesting the major role of Nectin-2 is for sperm mature." (PMID 31142324, 2019).
lung adenocarcinoma (3 papers, 2021 to 2025). A carcinoma that arises from the lung and is characterized by the presence of malignant glandular epithelial cells. "We performed immunohistochemical staining of 84 tumor segments from 22 resected tumor samples to evaluate the expression of PD-L1, PD-1, Nectin-2, PVR, and TIGIT in distinct growth patterns of lung adenocarcinoma." (PMID 34102454, 2021). "In several tumor entities, including lung adenocarcinoma, the expression of this regulatory receptor was found to be increased on TILs, giving tumor cells an additional option to escape the immune system in suppressing the functions of the TILs, when TIGIT binds one of its ligands Nectin-2 or PVR." (PMID 34102454, 2021).
lymph node metastasis (3 papers, 2015 to 2024). "The percentage of cases with positive Nectin-2 and DDX3 expression was significantly lower in PDAC patients without lymph node metastasis and invasion and having TNM stage I/II disease than in patients with lymph node metastasis, invasion, and TNM stage III/IV disease (P < 0.05 or P < 0.01)." (PMID 26294807, 2015).
mild cognitive impairment (3 papers, 2022 to 2024). "Though biological functions of NECTIN2 are still not fully understood, there is evidence that this gene can play roles in vulnerability to infections, progression of mild cognitive impairment to AD, and the formation of synapses, which may contribute to its effects on MMSE." (PMID 38408961, 2024).
osteosarcoma (3 papers, 2020 to 2024). A usually aggressive malignant bone-forming mesenchymal neoplasm, predominantly affecting adolescents and young adults. "Interestingly, NECTIN2–TIGIT interaction was enriched in proliferating TAMs and CD4_C3_CXCL13, CD4_C3_FOXP3 and CD8_C2_GNLY cell sub‐clusters, indicating that Proli_TAM may lead to T cell exhaustion in osteosarcoma PT tissues." (PMID 36305631, 2022).
adenocarcinoma of the pancreas (2 papers, 2015 to 2023). "In contrast, most of the pancreatic adenocarcinoma cases showed negative or focal staining for nectin-2 (median score: 1.0, mean score: 0.76) and nectin-4 (median score: 0, mean score: 0.67)." (PMID 25690753, 2015).
Bladder Cancer (2 papers, 2018 to 2023). "With external validation with RT-qPCR in a consecutive FUSCC cohort, we first give a clue that NECTIN2 might be a trigger for metastasis in bladder cancer pending larger cohorts and basic research." (PMID 29321541, 2018).
colon adenocarcinoma (2 papers, 2021 to 2024). "Therefore, in order to assess the antitumoral functions of NK cells derived from CRC pts, we performed a degranulation assay against the classical target cells of NK cells, K562 and human colon adenocarcinoma cell line (Caco-2), both expressing PVR and Nectin-2." (PMID 39126041, 2024).
delirium (2 papers, 2022 to 2026). A disorder characterized by confusion; inattentiveness; disorientation; illusions; hallucinations; agitation; and in some instances autonomic nervous system overactivity. "AD poses a risk for delirium, probably mediated by shared genetic variants NECTIN2 and TOMM40 that impact acetylcholine pathways." (PMID 41630310, 2026).
diabetes (2 papers, 2024 to 2025). "The CELF2-related AS events of NECTIN2, DYRK1B, SF1 and FN1 were significantly different and may be potential therapeutic targets for diabetes-related vascular disease." (PMID 40692719, 2025).
ductal carcinoma (2 papers, 2013 to 2023). "Expression of Nectin-1 and Nectin-2 was higher in ductal carcinomas than in all other histological types (Nectin-1: ductal 348+/−122 versus other 112+/−27, p = 0.063; Nectin-2: ductal 104+/−93 versus other 82+/−38, p = 0.0037)." (PMID 24386110, 2013). "Increased levels of nectin-2 were detected in ER tumors and in ductal carcinoma." (PMID 37568798, 2023).
esophageal squamous cell carcinoma (2 papers, 2023 to 2025). Esophageal squamous cell carcinoma (ESCC) is a type of esophageal carcinoma (EC) that can affect any part of the esophagus, but is usually located in the upper or middle third. "Similarly, in another histological type of cancer, such as squamous cell carcinoma of the esophagus, cytoplasmic expression of nectin-2 increases in poorly differentiated tumors." (PMID 40244005, 2025).
HCMV infection (2 papers, 2018). "Cluster 7 was enriched in proteins known to be degraded during HCMV infection, including the NK-activating ligand CD112/nectin cell adhesion molecule 2 (NECTIN2), as well as multiple “hits” from the inhibitor and pSILAC screens." (PMID 30122656, 2018).
metastatic disease (2 papers, 2013 to 2019). "Increased levels of Nectin-2 have also been found to be a biomarker for poor prognosis and metastatic disease in squamous cell and adenosquamous carcinoma and adenocarcinoma of the gallbladder." (PMID 24386110, 2013). "In comparison, Nectin-2, -3 and -4 were all reduced in patients with metastatic disease and those who had died of the disease." (PMID 24386110, 2013).
non-small cell lung carcinoma (2 papers, 2015 to 2024). A group of at least three distinct histological types of lung cancer, including non-small cell squamous cell carcinoma, adenocarcinoma, and large cell carcinoma. "Another study has also confirmed that NECTIN2-TIGIT co-localized significantly more in tumour than in background spots via single-cell and spatial transcriptomics analysis in non-small cell lung cancer." (PMID 39474422, 2024).